UBE3C (ubiquitin protein ligase E3C)
Diseases named in the same sentence as UBE3C in open-access papers (continued):
Sharing a sentence is not in itself a finding about the gene and the disease.
melanoma (1 paper, 2016). A malignant, usually aggressive tumor composed of atypical, neoplastic melanocytes. "Our aim was to elucidate the association between UBE3C and melanoma progression and to identify an alternative therapeutic target for the treatment of melanoma." (PMID 26894856, 2016). "Knockdown of UBE3C expression in melanoma cells significantly suppressed melanoma growth and progression." (PMID 26894856, 2016). "Associations between UBE3C and the epithelial-mesenchymal transition (EMT) markers E-cadherin and vimentin were also assessed in both melanoma tissues and cell lines." (PMID 26894856, 2016). "Melanoma cells that overexpressed UBE3C exhibited a mesenchymal phenotype, and UBE3C reduced the expression of E-cadherin in melanoma cells." (PMID 26894856, 2016). "Normal skin and other skin cancers with low metastatic capacities (i.e., SCC and BCC) showed lower UBE3C staining levels, suggesting that UBE3C plays a role in melanoma metastasis." (PMID 26894856, 2016). "Melanoma tissues with high UBE3C expression frequently showed low E-cadherin expression in the same patients." (PMID 26894856, 2016). "Melanoma cells overexpressing UBE3C frequently exhibited a mesenchymal phenotype, including reduced expression of the epithelial marker E-cadherin and expression of the mesenchymal marker vimentin." (PMID 26894856, 2016). "UBE3C expression was significantly associated with SCC tumor grade (P=0.002), age of primary melanoma patients (P=0.011) and TNM stage (P=0.011)." (PMID 26894856, 2016). "To investigate the function of UBE3C in melanoma, we used the A375 and SK-MEL-24 human melanoma cell lines to assess the impact of RNA interference (RNAi)-mediated UBE3C knockdown on the behavior melanoma cells." (PMID 26894856, 2016). "Subsequent functional experiments showed that UBE3C promoted melanoma progression by inducing EMT." (PMID 26894856, 2016). "Expression of UBE3C was detected mainly in the cytoplasm of melanoma cells." (PMID 26894856, 2016). "In addition, the functional relevance of UBE3C was further investigated using two human melanoma cell lines, A375 and SK-MEL-24." (PMID 26894856, 2016). "We also observed that melanoma cells overexpressing UBE3C exhibited a mesenchymal phenotype." (PMID 26894856, 2016). "Thus melanoma tissues, which have high metastatic capacity, showed the highest staining rate and the strongest intensity UBE3C staining." (PMID 26894856, 2016). "Thus UBE3C promotes melanoma progression, possibly by inducing epithelial-mesenchymal transition in melanoma cells." (PMID 26894856, 2016). "Inhibiting UBE3C activity may suppress melanoma invasion and metastasis and may represent a targeted therapeutic approach." (PMID 26894856, 2016). "Moreover, a higher proportion of melanoma tissues exhibited a UBE3Chigh/E-cadherinlow/vimentinhigh expression profile in which high levels of UBE3C expression were frequently accompanied by low levels of E-cadherin expression." (PMID 26894856, 2016). "In the present study, we investigated UBE3C expression in skin squamous cell cancer (SCC), skin basal cell cancer (BCC), primary melanoma (PM), and metastatic melanoma (MM)." (PMID 26894856, 2016). "However, further study will be required to clarify the specific relationship between UBE3C and E-cadherin, which functionally regulates the EMT process in melanoma cells." (PMID 26894856, 2016). "Thus inhibiting UBE3C expression may not only inhibit the growth and migration of melanoma cells, it may also restore E-cadherin expression, reverse the EMT phenotype, and attenuate the metastasis of melanoma cells." (PMID 26894856, 2016).
metastatic melanoma (1 paper, 2016). A melanoma that has spread from its primary site to another anatomic site. "In summary, the ubiquitin ligase UBE3C is overexpressed in both primary and metastatic melanoma tissues, where it plays a key role in disease development and progression." (PMID 26894856, 2016). "UBE3C levels were higher in both primary and metastatic melanoma than in normal skin and other skin cancers (SCC and BCC)." (PMID 26894856, 2016). "Moreover, we observed a link between UBE3C overexpression and reduced E-cadherin expression in both primary and metastatic melanoma." (PMID 26894856, 2016).
Parkinson disease (1 paper, 2020). A progressive degenerative disorder of the central nervous system characterized by loss of dopamine producing neurons in the substantia nigra and the presence of Lewy bodies in the substantia nigra and locus coeruleus. "The loci within these eQTL scores have been reported to regulate expression of genes involved in various brain-related processes and disorders, such as neurite outgrowth and Parkinson’s disease (DCAKD, SLC35A4, SEC14L4, SRA1, NMT1, CPNE1, PLEKHM1, UBE3C)." (PMID 32066731, 2020).
skin cancer (1 paper, 2016). "We next examined the relationships between UBE3C, E-cadherin and vimentin expression and the clinicopathological features associated with skin cancer." (PMID 26894856, 2016). "To investigate the role of UBE3C in skin cancer, we first performed an immunohistochemical analysis of UBE3C using two skin cancer tissue microarrays containing samples of human skin cancer and normal skin tissues." (PMID 26894856, 2016). "In the present study, we analyzed the expression of UBE3C and two typical EMT markers, E-cadherin and vimentin, in skin cancer and normal skin tissues." (PMID 26894856, 2016).
cancer (12 papers, 2015 to 2023). A tumor composed of atypical neoplastic, often pleomorphic cells that invade other tissues. "The mutations in the HECT domain of UBE3C often lead to pathophysiological states, including neurological disorders and human cancers." (PMID 25658088, 2015). "Recently just one study reported that the high frequency of UBE3C mutations in HCC provides a preliminary connection between UBE3C and human cancer, UBE3C was over-expressed in HCC tissues and promoted HCC progression, extending its role in cancer development." (PMID 25658088, 2015). "It has been shown in previous studies that the E3 ubiquitin ligases, such as RNF146, TRIM11, TRIM32, TRIM54, TRIM65 and UBE3C promote various cancers by triggering Wnt/β-catenin signaling via degradation of Axin1." (PMID 37379772, 2023). "In BRCA, UBE3C has been found to activate proliferation, migration, and invasion of cancer cells in vitro by triggering the nuclear translocation of β-catenin, a master factor associated with tumor development." (PMID 37173692, 2023). "UBE3C (also known as HECTH2) is an E3 ligase, and mutations in the HECT domain of UBE3C can lead to pathophysiological states, such as neurological impairments and cancer in humans." (PMID 37173692, 2023). "Several studies have reported that UBE3C acts as a ubiquitin E3 ligase and participates in the ubiquitination of key molecules in cancers." (PMID 35840930, 2022). "UBE3C has been defined as a significant cancer-related functional protein that promotes cancer metastasis and growth in multiple cancers, including melanoma, renal cell carcinoma, and non-small cell lung cancer." (PMID 33407510, 2021). "Ubiquitin-protein ligase E3C (UBE3C)-mediated ubiquitination is involved in sustaining the CSC (cancer stem cells) properties of NSCLC." (PMID 34502538, 2021). "The ubiquitin-protein ligase E3C (UBE3C) belongs to the E3 ligase enzyme family and implicates in the ubiquitin-proteasome pathway, thus regulates physiological and cancer-related processes." (PMID 26067607, 2015). "In addition to the diagnostic and prognostic value of UBE3C, several scholars have found that targeting UBE3C is a promising therapeutic strategy to limit cancer progression." (PMID 33407510, 2021). "Besides, the ubiquitin protein ligase E3C (UBE3C), a direct target of miR-30a-5p, plays important roles in cancers through the mutation in the HECT domain and Wnt/β-catenin signal pathway." (PMID 30158978, 2018). "LINC00355 was shown to promote cancer cell proliferation and tumor growth in xenograft animals by regulating the transcription of three genes (ITGA2, RAD18, and UBE3C) and participating in seven ceRNA axes." (PMID 38125763, 2023). "LINC00355 was shown to promote invasion and migration in cancer cells and xenograft animals by regulating the transcription of three downstream genes (ITGA2, RAD18, and UBE3C) and participating in six ceRNA axes." (PMID 38125763, 2023). "UBE3C, another member of the HECT E3 family, has been reported to play a critical role in multiple cancers." (PMID 33407510, 2021).
tumor (11 papers, 2015 to 2025). "High nuclear UBE3C expression was associated with an advanced tumor node metastasis classification (TNM) stage and a poor survival status." (PMID 33407510, 2021). "The association between the ubiquitin ligase UBE3C and tumor progression was recently established by several studies." (PMID 26894856, 2016). "Supporting this hypothesis, protein-protein interaction networks and epigenetic regulatory analyses revealed that SEC61G, PGAM1, and UBE3C are closely linked in processes such as protein ubiquitination and tumor metabolic regulation." (PMID 39990664, 2025). "The parental and R cells, with corresponding UBE3C-kd or UBE3C-ki induction, were further transfected with luciferase and injected into mice intracardiacally to analyze tumor cell metastasis." (PMID 37173692, 2023). "We found ten E3 enzymes, among which TRIM21, UBR5 and UBE3C have been widely reported to be involved in tumor metastasis." (PMID 37422473, 2023). "Regarding its mechanism of action, UBE3C induces the proteasomal degradation of Annexin A7: this protein is believed to act as a tumor suppressor in GBM via attenuation of the epidermal growth factor receptor (EGFR) signaling." (PMID 33665742, 2021). "We postulated that UBE3C regulates the Wnt/β-catenin signaling pathway to mediate tumor growth and metastasis in BrCa cells." (PMID 33407510, 2021). "We next evaluated the expression levels of UBE3C in the nucleus and cytoplasm in BrCa tissues compared with breast tissues, and the results showed that most tumor samples exhibited higher UBE3C expression in the nucleus and cytoplasm." (PMID 33407510, 2021). "MiR-30a has also been demonstrated to inhibit several critical oncogenes, such as Eya2, ITGB3, or UBE3C, and suppress tumor growth, cell migration and invasion." (PMID 29162923, 2017). "Aberrant expression of ubiquitin-protein ligase E3C (UBE3C) plays a key role in tumor development and progression." (PMID 26894856, 2016). "For instance, ubiquitin-protein ligase E3C (UBE3C) is an important tumor-related regulatory molecule that promotes both tumor growth and metastasis." (PMID 26894856, 2016). "We found that UBE3C knockdown in both cell lines significantly suppressed cell proliferation, migration and invasion in vitro and tumor growth in vivo." (PMID 26894856, 2016). "We analysized the UBE3C protein expression in tumor specimens derived from 267 postoperative ccRCC patients whose 5-year follow-up data were available." (PMID 25658088, 2015). "We postulated that UBE3C activates Wnt/β-catenin signal pathway in order to promote tumor growth and metastasis in RCC cells." (PMID 25658088, 2015). "Tumor grade and UBE3C expression were independent prognostic predictors of both OS (p = 0.014) and PFS (p = 0.004, respectively), while Tumor grade was an independent prognostic indicator of OS (p = 0.037)." (PMID 26067607, 2015). "The UBE3C over-expression in ccRCC tumor tissues showed a positive correlation with TNM stage (r = 0.731, P<0.01)." (PMID 25658088, 2015). "Clinically, UBE3C overexpression significantly correlated with high-grade tumors (p < 0.05), poor overall survival, and early tumor recurrence." (PMID 26067607, 2015). "Developing SEC61G-specific inhibitors or disrupting its interaction with UBE3C could effectively suppress tumor glycolysis and prevent metastases." (PMID 39990664, 2025). "Positive UBE3C staining was detected in the cytoplasm of tumor cells." (PMID 26067607, 2015). "Additionally, UBE3C could function as a correct prognosis biomarker, since higher levels of UBE3C expression were detected in patients with aggressive clinicopathological characteristics, such as high tumor grade, metastasis, and poor differentiation." (PMID 33665742, 2021). "Univariate analysis showed that high tumor stage, positive glial fibrillary acidic protein (GFAP) expression, radiochemotherapy, total resection, and high UBE3C expression were predictors for OS and PFS." (PMID 26067607, 2015).
tumor (continued). "Together, SEC61G may regulate PGAM1 stability and activity by modulating UBE3C-mediated ubiquitination, providing new insights into the role of SEC61G in tumor metabolic reprogramming." (PMID 39990664, 2025). "UBE3C is reportedly involved in the growth and metastasis in several types of solid tumors, possibly by inducing EMT, activating the Wnt/β-catenin pathway, and/or degrading various tumor-related proteins." (PMID 26894856, 2016).
neurological disease (3 papers, 2015 to 2025). "Considering a rather strong evidence of UBE3C involvement in the pathology of several human neurological diseases, future research should elucidate the cellular and molecular outcomes of UBE3C enzymatic activity and K29 ubiquitination in developing cortex." (PMID 33182779, 2020).
UBE3C also shares sentences with these, for which no sentence is quoted: autism spectrum disorder (2 papers); acute lymphoblastic leukemia (1); Behcet’s syndrome (1); cutaneous squamous cell carcinoma (1); diabetic kidney disease (1); Follicular Cyst (1); infection (1); Kaufman oculocerebrofacial syndrome (1); nasal polyps (1); neurodevelopmental disorder (1); skin basal cell carcinoma (1).